TNKS (tankyrase)
Diseases named in the same sentence as TNKS in open-access papers (continued):
Sharing a sentence is not in itself a finding about the gene and the disease.
epilepsy (2 papers, 2021 to 2023). A brain disorder characterized by episodes of abnormally increased neuronal discharge resulting in transient episodes of sensory or motor neurological dysfunction, or psychic dysfunction. "Considering the important role of Wnt/beta-catenin signaling and PTEN in the brain, it is possible that TNKS confers risk of epilepsy by regulating Wnt/beta-catenin signaling pathway." (PMID 34456681, 2021). "Of note, we identified three risk genes (TTC21B, RP11-375N15.2, and TNKS) whose expression perturbation may have a role in epilepsy." (PMID 34456681, 2021). "However, further genetic studies and functional characterization are needed to validate if TNKS is a risk gene for epilepsy." (PMID 34456681, 2021). "In addition, we also identified three genes (TTC21B, RP11-375N15.2, and TNKS) whose cis-regulated expression level are associated with epilepsy, indicating that risk variants may confer epilepsy risk through regulating the expression of these genes." (PMID 34456681, 2021). "A TWAS has suggested three significant risk genes for epilepsy: tetratricopeptide repeat domain 21 B (TTC21B), RP11-375N15.2, and tankyrase (TNKS)." (PMID 37246165, 2023). "In conclusion, our study not only provides new insights into genetic architecture of epilepsy but also prioritizes potential molecular targets (including GRM3 and TNKS) for development of new drugs and therapeutics for epilepsy." (PMID 34456681, 2021). "Second, our TWAS results suggested that TNKS is a gene whose genetically regulated expression may have a role in epilepsy." (PMID 34456681, 2021).
lung fibrosis (2 papers, 2019 to 2024). "In addition, the potential therapeutic implications of tankyrase inhibitors are not limited to oncology but has also disseminated to multiple sclerosis, pulmonary fibrosis, and lipid disorder, highlighting the need for minimizing off-target effects and toxicity." (PMID 37741944, 2024).
ovarian tumor (2 papers, 2014 to 2022). "It is reported that TNKS is upregulated in ovarian tumor tissue and its upregulation is negatively correlated with patient survival." (PMID 36185280, 2022). "PARP1 and PARP2 inhibitors have been developed for breast and ovarian tumors manifesting double-stranded DNA-repair defects, whereas tankyrase 1 and 2 (TNKS1 and TNKS2, also known as PARP5a and PARP5b, respectively) inhibitors have been developed for tumors with elevated β-catenin activity." (PMID 25286857, 2014).
viral infections (2 papers, 2025 to 2026). "Finally, we consider therapeutic implications of disrupting TNKS-protein interactions, with particular attention paid to selective small-molecule inhibitors and their translational potential in cancer, viral infections, and degenerative diseases." (PMID 41744791, 2026).
acute promyelocytic leukemia (1 paper, 2020). An aggressive form of acute myeloid leukemia (AML), characterized by arrest of leukocyte differentiation at the promyelocyte stage, due to a specific chromosomal translocation t(15;17) in myeloid cells. "Tankyrase inhibitor IWR-1, in combination with treatment with salinomycin (SAL), synergistically triggered SAL-induced differentiation of acute promyelocytic leukemia (APL) cells by inhibiting Wnt–β-catenin signaling." (PMID 32872365, 2020).
autism (1 paper, 2023). Persistent deficits in social interaction and communication and interaction as well as a markedly restricted repertoire of activity and interest as well as repetitive patterns of behavior. "In utero injection of XAV939, a tankyrase inhibitor that subsequently activates β-catenin signaling, induced autism-like behaviors such as impaired sociability in mice." (PMID 37524878, 2023).
central obesity (1 paper, 2011). "Another candidate gene located near MSRA, the TRF1-interacting ankyrin-related ADP-ribose polymerase (TNKS), has been proposed as the causal gene for the association with central obesity." (PMID 21674055, 2011).
dyslipidemia (1 paper, 2020). "In this study we demonstrate that inhibition of TNKS activity prevents body weight gain, restrains fat accumulation, and alleviates dyslipidemia." (PMID 32317752, 2020).
endothelial dysfunction (1 paper, 2024). In vascular diseases, endothelial dysfunction is a systemic pathological state of the endothelium (the inner lining of blood vessels) and can be broadly defined as an imbalance between vasodilating and vasoconstricting substances produced by (or acting on) the endothelium. "Based on our results, it is therefore tempting to speculate that the use of ROCK inhibitors, such as fasudil, in conjunction with tankyrase inhibitors might prove a potential strategy to limit at least the endothelial dysfunction." (PMID 37741944, 2024).
enteritis (1 paper, 2019). Inflammation of the small intestine. "Because no obvious enteritis was observed in our in vivo administration of G007-LK, an additional investigation may be required to determine if G-631-induced intestinal toxicity is due to tankyrase-specific suppression or if it is a non-specific effect of the drug." (PMID 30813388, 2019).
HCMV infection (1 paper, 2015). "Thus, although use of XAV939 sheds light on the requirement for inactivating TNKS for HCMV infection, HCMV-mediated control of β-catenin may involve additional Wnt proteins that are not directly controlled by TNKS." (PMID 26729153, 2015). "The accumulation of TNKS during HCMV infection and resulting Axin1 stabilization and decrease in β-catenin expression is a unique feature of HCMV infection." (PMID 26729153, 2015). "Since downregulation of TNKS activity was an HCMV-driven mechanism, we investigated the effects of TNKS inhibition on the expression of Wnt pathway proteins during HCMV infection." (PMID 26729153, 2015). "Since transcriptional change or protein degradation did not seem to play a role in TNKS accumulation, we hypothesized that HCMV infection could influence the enzymatic activity of TNKS." (PMID 26729153, 2015). "Thus, HCMV infection does not reduce protein PARsylation in general, but specifically inhibits the PARsylation activity of TNKS." (PMID 26729153, 2015). "However, TNKS-mediated regulation may not be the only mechanism leading to Axin1 stabilization in HCMV infection." (PMID 26729153, 2015).
Herpes simplex viral infections (1 paper, 2021). "Due to the importance of tankyrase in Wnt/β-catenin signaling, using TNKS inhibitor in several diseases including cancer (colon, lung, and prostate), cherubism, and systemic sclerosis, Epstein Barr and Herpes simplex viral infections, fibrotic diseases, and others have been investigated before." (PMID 35194449, 2021).
hypospadias (1 paper, 2020). Hypospadias is the displacement of the urethral meatus on the ventrum of the penis. "Within these regions, we further identified that expression of genes regulating beta-catenin are related to hypospadias, including UBE2R234 (ubiquitin-conjugating enzyme), PKP235 (plakophilin), and TNKS36 (tankyrase)." (PMID 32728162, 2020).
inflammatory bowel disease (1 paper, 2022). A spectrum of small and large bowel inflammatory diseases of unknown etiology. "Mice lacking tankyrase in myeloid cells develop severe inflammatory bowel disease and elevated serum cytokine levels." (PMID 35362478, 2022).
ischemic stroke (1 paper, 2022). A stroke disorder caused by obstruction of blood flow to the brain, due to thrombotic (local blood clot formation) or embolic (due to a blood clot or other material traveling from another site) event. "The association of TNKS and TNKS2 with CVD and ischemic stroke risk has also been identified by a whole genome survey of Caucasian women." (PMID 36077457, 2022).
liver steatosis (1 paper, 2020). "TNKS inhibition also stimulates lipid oxidation in muscle and decreases liver steatosis." (PMID 32317752, 2020).
lupus (1 paper, 2019). "Therefore, tankyrase inhibition might potentially ameliorate immunological abnormalities associated with lupus induction and progression." (PMID 31052273, 2019).
lymphoma (1 paper, 2003). A malignant (clonal) proliferation of B- lymphocytes or T- lymphocytes which involves the lymph nodes, bone marrow and/or extranodal sites. "We found similar levels of TRF1 and tankyrase expression in all lymphomas studied." (PMID 12915884, 2003).
medulloblastoma (1 paper, 2015). A malignant, invasive embryonal neoplasm arising from the cerebellum. "In addition, ARTD-5, or Tankyrase (TNKS), is a positive regulator of the WNT signaling implicated in the development and biological behavior of many neoplasms, such as Medulloblastoma (MB), in which radiotherapy is an essential part of the treatment." (PMID 25835728, 2015).
myopia (1 paper, 2024). "Researchers indicate that PAX6 rs644242, ZC3H11B rs4373767 and BICC1 rs7084402, VIPR2 rs885863 and rs6979985, ZMAT4 rs7829127, TNKS rs4840437 and rs6989782, PDGFRA rs2114039, SOX2 rs4575941, FGF10 rs339501, rs2973644, and rs 79002828 are associated with severe myopia (moderate and extreme myopia)." (PMID 38660258, 2024).
Nephropathy (1 paper, 2016). A nonspecific term referring to disease or damage of the kidneys. "However, it did not significantly reduce the increased expression of fibronectin, further increased the expression of LEF1, upregulated PAI-1 (CD2AP−/−+tankyrase inhibitor), a fibrogenic factor that has been associated with the development of nephropathy, and increased pro-apoptotic signaling." (PMID 27441654, 2016).
non-small cell lung carcinoma (1 paper, 2018). A group of at least three distinct histological types of lung cancer, including non-small cell squamous cell carcinoma, adenocarcinoma, and large cell carcinoma. "In X-ray-irradiated non-small cell lung cancer cells, tankyrase localized to DNA double-stranded break sites in a MERIT40-dependent manner." (PMID 30533199, 2018).
oral mucositis (1 paper, 2024). Inflammation of the mucous membranes of any of the structures in the mouth. "- The SNP rs117157809 located in TNKS gene was associated with increased risk of oral mucositis (95% CI 2.10–6.57; p = 6.33 × 10−6)." (PMID 38473311, 2024).
pancreatic ductal adenocarcinoma (1 paper, 2019). An infiltrating adenocarcinoma that arises from the epithelial cells of the pancreas. "Targeting the WNT pathway with the specific tankyrase (TNKS) inhibitor, XAV-939, can enhance the immune response against pancreatic ductal adenocarcinoma (PDAC) cells with lymph node-positive metastasis." (PMID 31575023, 2019).
renal carcinoma (1 paper, 2025). A carcinoma arising from the epithelium of the renal parenchyma or the renal pelvis. "This study aims to identify novel dual inhibitors of tankyrase and Cyclin-dependent kinase 8 (CDK8), utilizing bioinformatics and in vitro methods and to assess their efficiency in renal cancer cells." (PMID 40699862, 2025).
sarcoma (1 paper, 2012). A usually aggressive malignant neoplasm of the soft tissue or bone. "We also demonstrated that tankyrase inhibitors induce Axin1/2 stabilization in human MDA-MB-231 basal-like cells, human MCF-7 epithelial-like cells and mouse EMT6 sarcoma-like cells, all of which are breast cell lines of diverse origins but with normal APC." (PMID 23144924, 2012).
schizophrenia (1 paper, 2017). A major psychotic disorder characterized by abnormalities in the perception or expression of reality. "Further, we identified three loci shared between neuroticism and schizophrenia, which were annotated to FLJ10661 (rs2945232; non-coding transcript exon variant), TNKS (rs2048656; intergenic) and EP300 (rs11090039; intronic)." (PMID 28533504, 2017).
seminoma (1 paper, 2023). A radiosensitive malignant germ cell tumor found in the testis (especially undescended), and extragonadal sites (anterior mediastinum and pineal gland). "We treated GCT cell lines GCT44 and 1411H (YST), NTERA-2 (EC) and TCam2 (seminoma) with two different WNT inhibitors: the tankyrase inhibitor IWR-1 and the PORCN inhibitor LGK-974." (PMID 37149691, 2023).
steatosis (1 paper, 2020). Increased lipid within the cytoplasm of cells. "TNKS inhibition reduced body weight gain, abdominal fat content, serum cholesterol levels, steatosis, and proteins associated with lipolysis in diabetic db/db mice." (PMID 32317752, 2020).
ventricular dilatation (1 paper, 2022). "In an isoproterenol-induced HF zebrafish model, inhibition of TNKS activity with XAV939, a TNKSs-specific inhibitor, protected against ventricular dilatation and cardiac dysfunction and abrogated overactivation of Wnt/β-catenin signaling and dysregulation of miR-34a-5p induced by isoproterenol." (PMID 36077457, 2022).
Werner syndrome (1 paper, 2010). "Interestingly, PARP, and DNA-PKcs have been shown to interact/cooperate with WRN, the protein mutated in the premature aging Werner syndrome, raising the possibility of tankyrase 1 specific involvement in aging." (PMID 21037379, 2010).
cancer (111 papers, 2006 to 2026). A tumor composed of atypical neoplastic, often pleomorphic cells that invade other tissues. "While this dual approach enhances anti-cancer efficacy, it also poses a higher risk of toxicity due to tankyrase’s diverse cellular roles." (PMID 40001540, 2025). "Since aberrant Wnt signaling is often associated with various cancers, TNKS enzymes are considered potential pharmacological targets for anti-tumor agents." (PMID 32664504, 2020). "One challenge associated with the development of tankyrase inhibitors as a treatment for cancer has been the intestinal toxicity observed in pre-clinical animal models." (PMID 30655555, 2019). "The inhibition of tankyrase is reported to exhibit an anti-cancer effect against BRCA1/2-deficient and Wnt-dependent cancers as well as a universal anti-cancer effect through the stabilization of TRF1 and a concomitant inhibition of telomerase function." (PMID 30813388, 2019). "Tankyrase-mediated PARylation of axin results in its K48-linked polyubiquitination and proteasomal degradation, thereby stabilizing β-catenin and promoting cancer cell growth." (PMID 29263426, 2017). "Tankyrase substrates include a growing number of tumor suppressors, whose inactivation is implicated in cancer development and progression." (PMID 28877210, 2017). "The inhibition of tankyrase and telomerase caused telomere shortening and apoptosis, which has been proposed as a potential cancer therapy." (PMID 19270793, 2009). "Furthermore, tankyrase inhibition disrupts AJ assembly by preventing F-actin anchoring to cadherins, a process associated with cancer cell adhesion and metastasis." (PMID 40001540, 2025). "While PPP6R2 is a regulatory protein implicated in cell cycle entry and progression whose loss of function causes genomic instability, TNKS is involved in the Wnt pathway whose destabilization and deregulation led to uncontrolled proliferation and, therefore, progression of cancers." (PMID 37175550, 2023). "The top CpG site associated with binary response is located in TNKS, which is a protein-coding gene associated with blood pressure, alcohol consumption, implicated in cancer pathology, and involved in various processes such as the Wnt signaling pathway, telomere length, and vesicle trafficking." (PMID 34091594, 2021). "Thus, Tankyrase inhibitors have been extensively investigated for the treatment of clinical conditions associated with activated Wnt signaling such as cancer and fibrotic diseases." (PMID 33028869, 2020). "Silencing of tankyrase elicits synthetic lethality in BRCA1/2-deficient cancer cells." (PMID 31836723, 2019). "Additionally, cells (particularly cancer cells) may find a way to compensate for the loss of tankyrase during clonal outgrowth." (PMID 29263426, 2017). "Stabilization of AXIN1 and AXIN2 by inhibiting their degradation through tankyrase (TNKS) allows the attenuation of Wnt signaling in cancer, attracting interest for potential targeted therapy." (PMID 39022865, 2025). "XAV939 is the prototypical tankyrase inhibitor and was used at the same concentration generally admitted in cell culture experiments to achieve its inhibitory activity on cancer cells." (PMID 37741944, 2024). "It was found out that TNKS is a feasible target to inhibit the Wnt/β-catenin signal transduction that is improperly activated in many cancers." (PMID 38731421, 2024). "Taken together, these results paved, the way for the development of novel TNKS inhibitors based on this chemical structure to treat Wnt-dependent cancers." (PMID 38731421, 2024). "TNKS-1/2 have been investigated as a therapeutic target for the Wnt signaling pathway-dependent cancers." (PMID 38338721, 2024). "This action competes with RNF146-mediated degradation, leading to stabilization of tankyrase and its binding partner, Angiomotin, a cancer cell signaling protein." (PMID 37938264, 2023).